MKX (mohawk homeobox)
Description:
May act as a morphogenetic regulator of cell adhesion.
Synonyms: C10orf48; IRXL1; MGC39616; IFRX
Tractability: No criterion of Open Targets' tractability assessment is met for any kind of drug.
Gene: Protein-coding gene on chromosome 10 (27,672,874 to 27,746,060, reverse strand). Ensembl gene ENSG00000150051.
Subcellular location: Nucleus
Subcellular location (Human Protein Atlas): Nuclear speckles; Nucleoplasm
Gene Ontology:
Molecular function: DNA-binding transcription factor activity, RNA polymerase II-specific; RNA polymerase II cis-regulatory region sequence-specific DNA binding; DNA binding
Biological process: cell development; muscle organ development; regulation of transcription by RNA polymerase II; regulation of DNA-templated transcription
Cellular component: chromatin; nucleus
Genetic constraint (gnomAD): Loss-of-function variants: 13 observed, 35.94 expected, observed/expected ratio (o/e) 0.36, 90% interval 0.23 to 0.57. The upper end of that interval is the gene's LOEUF score, 0.57, which puts it in group 2 of 6, group 1 being the genes least tolerant of losing a copy. Missense variants: 458 observed, 459.53 expected, observed/expected ratio (o/e) 1, 90% interval 0.92 to 1.08. Synonymous variants: 176 observed, 175.68 expected, observed/expected ratio (o/e) 1, 90% interval 0.88 to 1.13.
Homologues: Orthologues: chimpanzee MKX (99% identical), macaque MKX (98% identical), pig MKX (94% identical), guinea pig MKX (94% identical), rabbit MKX (91% identical), mouse Mkx (89% identical), rat Mkx (88% identical), tropical clawed frog mkx (80% identical), zebrafish mkxa (69% identical), Drosophila melanogaster CG11617 (24% identical). Paralogues in human: IRX3 (24% identical), IRX1 (24% identical), IRX4 (23% identical), IRX5 (22% identical), IRX6 (21% identical), IRX2 (21% identical).
Diseases named in the same sentence as MKX in open-access papers:
MKX is named in the same sentence as 27 diseases in open-access papers, as found by Europe PMC text mining. Sharing a sentence is not in itself a finding about the gene and the disease. The quoted sentences say what the papers report.
Obesity (2 papers, 2023). Accumulation of substantial excess body fat. "MKX is a potential regulator of brown adipose tissue development associated with obesity-related metabolic dysfunction in children." (PMID 37662987, 2023). "In summary, the expression of COBL, MKX and MYOC in AT is related to obesity, AT dysfunction, and the early signs of metabolic disease in children." (PMID 36834493, 2023). "Furthermore, COBL, MKX and MYOC expression in the subcutaneous AT of children is related to obesity and parameters of AT dysfunction and metabolic disease, such as adipocyte size, leptin levels and HOMA-IR." (PMID 36834493, 2023). "Finally, we provide evidence that the expression of COBL, MKX and MYOC in subcutaneous AT is related to obesity, parameters of AT dysfunction, and the early signs of metabolic disease in children." (PMID 36834493, 2023). "We detected significantly decreased expressions of COBL and MKX in subcutaneous AT samples of children with overweight and obesity compared to lean children, while the expression of MYOC was not altered with obesity." (PMID 36834493, 2023).
ovarian carcinoma (2 papers, 2017 to 2023). A malignant neoplasm originating from the surface ovarian epithelium. "One study showed a relationship between MKX methylation levels and the progression-free survival of ovarian cancer patients undergoing platinum chemotherapy." (PMID 37242540, 2023). "MKX (IRXL1) is known for its role in muscle development; recently, it has been identified as an epigenetically regulated gene by microRNA 662 in ovarian cancer, but its role in ovarian cancer is unknown." (PMID 28641578, 2017).
tendinopathy (2 papers, 2017 to 2025). "To elucidate the relevance of Hh signaling activation in human tendon injury, we also examined the expression of GLI1 and MKX in human tendinopathy specimens." (PMID 29244023, 2017). "Furthermore, co-localization of GLI1+ and MKX+ cells is also found in human tendinopathy specimens." (PMID 29244023, 2017).
Alzheimer disease (1 paper, 2025). A progressive, neurodegenerative disease characterized by loss of function and death of nerve cells in several areas of the brain leading to loss of cognitive function such as memory and language. "Our analysis identified several transcription factors with no previous association with Alzheimer's disease in astrocytes, including TOX3, MKX, ZBTB18, and ZNF382." (PMID 40656638, 2025).
breast carcinoma (1 paper, 2020). "On 10p12.1, rs2642278 was positively associated with DA and breast cancer risk, and an eQTL for MKX (mohawk homeobox), which plays a role in cell adhesion." (PMID 33037222, 2020). "Five additional loci were newly associated with both DA and breast cancer risk in the same direction, identifying LMNB1, MKX, PRKG1, MRPL17, and SMIM25 as candidate genes for both DA and breast cancer risk." (PMID 33037222, 2020).
cervical cancer (1 paper, 2017). A primary or metastatic malignant neoplasm involving the cervix. "Interestingly, we previously identified MKX hypermethylation as an early detection biomarker for cervical cancer." (PMID 28641578, 2017).
colorectal adenoma (1 paper, 2018). An adenoma that arises from the colon or rectum. "Using genome-wide DNA methylation analysis, we identified novel aberrant methylation profiles of genes including HLX, CUX2, MKX, NRG3 and PDGFRA associated with the colorectal adenoma-carcinoma sequence progression." (PMID 29945573, 2018).
colorectal cancer (1 paper, 2024). A primary or metastatic malignant neoplasm that affects the colon or rectum. "Aberrant expression of MKX has also been described in colorectal cancer, suggesting a wider role in carcinogenesis." (PMID 39689089, 2024).
endometrial cancer (1 paper, 2023). Primary or metastatic malignant neoplasm involving the endometrium (mucous membrane that lines the endometrial cavity). "However, the results were opposite in urothelial, stomach, renal, and endometrial cancers, for which low MKX expression was associated with better survival outcomes." (PMID 37242540, 2023).
esophageal adenocarcinoma (1 paper, 2023). A malignant tumor with glandular differentiation arising predominantly from Barrett mucosa in the lower third of the esophagus. "In addition, a regression analysis of TCGA Esophageal Adenocarcinoma patients revealed that patients with medium MKX expression status had significantly better overall survival (HR= 0.46; 95%CI = (0.218–0.99); p = 0.047) compared to cases with low MKX expression status." (PMID 37242540, 2023).
esophageal cancer (1 paper, 2023). A primary or metastatic malignant neoplasm involving the esophagus. "Clinical evidence suggests that the expression of MKX and its association with oxaliplatin may have some efficacy in the treatment of esophageal cancer, but further research is needed to confirm these results." (PMID 37242540, 2023). "Therefore, assessing MKX/MKXAS1 expression, MMR status, and MSI can be crucial in determining prognosis and guiding treatment decisions for gastric, pancreatic, and esophageal cancers." (PMID 37242540, 2023).
Insulin resistance (1 paper, 2023). Increased resistance towards insulin, that is, diminished effectiveness of insulin in reducing blood glucose levels. "In addition to that, MKX but not COBL expression showed an inverse and BMI SDS-independent association with serum leptin levels (Radjusted = −0.168, padjusted = 0.028) and the insulin resistance marker HOMA-IR (Radjusted = −0.211, padjusted = 0.003)." (PMID 36834493, 2023).
multiple myeloma (1 paper, 2024). "Screening of these RNA-seq data demonstrated prominent MKX expression in AML cell line OCI-AML3, low levels in multiple myeloma (MM) cell lines KMM-1, L-363, LP-1 and OPM-2, while cell lines derived from other entities including BCP-ALL tested negative." (PMID 39689089, 2024). "Screening of public datasets revealed silent MKX in normal myelopoiesis and B-cell differentiation, and aberrant expression in subsets of AML and multiple myeloma (MM) cell lines and patients." (PMID 39689089, 2024).
osteoarthritis (1 paper, 2024). A noninflammatory degenerative joint disease occurring chiefly in older persons, characterized by degeneration of the articular cartilage, hypertrophy of bone at the margins and changes in the synovial membrane. "In human osteoarthritis patients, anterior cruciate ligament-derived cells showed reduced MKX expression, suggesting that reduced MKX expression is associated with the degeneration of the anterior cruciate ligament." (PMID 38886383, 2024).
serous ovarian cancer (1 paper, 2023). "For example, high FZD10, MKX, FAM83A and MYO18B methylation were related with response to platinum-based chemotherapy in advanced stage high-grade serous ovarian cancer (HGSOC), and these markers might be used to predict platinum sensitivity in HGSOC patients." (PMID 37732324, 2023).
thyroid cancer (1 paper, 2023). "Our findings of high MKX expression being associated with better survival outcomes were supported by similar observations available in the Human Protein Atlas (proteinatlas.org) in colon, liver, lung, and thyroid cancers." (PMID 37242540, 2023).
cancer (3 papers, 2018 to 2024). A tumor composed of atypical neoplastic, often pleomorphic cells that invade other tissues. "This hypothesis was supported by recent publications, reporting that DNA methylation at MKX and other homeobox genes was detected in solid tumors via a pan-cancer screen, and that OCI-AML3 carries a pediatric AML-associated mutation in DNMT3A." (PMID 39689089, 2024).
metabolic disease (1 paper, 2023). A congenital disorder (due to inherited enzyme abnormality) or acquired (due to failure of a metabolically important organ) disorder resulting from an abnormal metabolic process. "However, a regulatory function of MKX in AT and in white or brown adipocyte differentiation has not been investigated in detail so far and there is no data on a potential association of MKX with metabolic disease in humans." (PMID 36834493, 2023). "Furthermore, we provide evidence that the AT expression of COBL, MKX and MYOC is related to early signs of AT dysfunction and metabolic disease in children, indicating a potential role in the pathogenesis of these processes." (PMID 36834493, 2023).
tumor (1 paper, 2024). "Therefore, aberrant MKX activity may curb this seeming apoptotic predisposition, enhancing survival of the tumor cells." (PMID 39689089, 2024).
MKX also shares sentences with these, for which no sentence is quoted: infection (3 papers); acute myeloid leukemia (1); cleft lip (1); cleft palate (1); colon cancer (1); herpes zoster (1); lung adenocarcinoma (1); otitis media (1).